CA10 (carbonic anhydrase 10 (inactive))
Description:
Does not have a catalytic activity.
Synonyms: hucep-15; CARPX; CA-RPX
Tractability: Small molecule: it belongs to a druggable protein family.
Gene: Protein-coding gene on chromosome 17 (51,630,313 to 52,160,017, reverse strand). Ensembl gene ENSG00000154975.
Subcellular location (Human Protein Atlas): Vesicles; Predicted to be secreted
Gene Ontology:
Molecular function: carbonate dehydratase activity; neurexin family protein binding; zinc ion binding
Biological process: brain development
Cellular component: synapse
Genetic constraint (gnomAD): Loss-of-function variants: 11 observed, 26.69 expected, observed/expected ratio (o/e) 0.41, 90% interval 0.26 to 0.68. The upper end of that interval is the gene's LOEUF score, 0.68, which puts it in group 2 of 6, group 1 being the genes least tolerant of losing a copy. Missense variants: 252 observed, 315.56 expected, observed/expected ratio (o/e) 0.8, 90% interval 0.72 to 0.89. Synonymous variants: 121 observed, 111.52 expected, observed/expected ratio (o/e) 1.09, 90% interval 0.94 to 1.26.
Homologues: Orthologues: chimpanzee CA10 (100% identical), dog CA10 (100% identical), guinea pig CA10 (100% identical), mouse Car10 (100% identical), pig CA10 (100% identical), rabbit CA10 (100% identical), rat Car10 (100% identical), macaque CA10 (95% identical), tropical clawed frog ca10 (89% identical), zebrafish ca10b (74% identical), Drosophila melanogaster CARPB (39% identical), Caenorhabditis elegans cah-1 (30% identical), and 7 more. Paralogues in human: CA11 (53% identical), CA2 (28% identical), CA5B (27% identical), CA7 (27% identical), CA13 (26% identical), CA3 (26% identical), CA5A (26% identical), CA1 (25% identical), CA9 (24% identical), CA12 (24% identical), CA8 (24% identical), CA14 (23% identical), and 2 more.
Diseases named in the same sentence as CA10 in open-access papers:
CA10 is named in the same sentence as 17 diseases in open-access papers, as found by Europe PMC text mining. Sharing a sentence is not in itself a finding about the gene and the disease. The quoted sentences say what the papers report.
chondroblastoma (1 paper, 2022). A benign, chondroid-producing, well-circumscribed, lytic neoplasm usually arising from the epiphysis of long bones. "CA10 is regarded as a functional gene in the central nervous system, and Chondroblastoma and Non-Suppurative Otitis Media are two diseases linked to CA10." (PMID 36414950, 2022).
developmental delay (1 paper, 2025). "For instance, CA10 is implicated in bone metabolism and bone development, ASAP1 is an important candidate gene affecting the growth and body size of Tibetan sheep, and biallelic variants of CSMD1 cause developmental delay." (PMID 40128652, 2025).
glioma (1 paper, 2019). A benign or malignant brain and spinal cord tumor that arises from glial cells (astrocytes, oligodendrocytes, ependymal cells). "We also looked at CA10 expression in the REMBRANDT glioma dataset and TCGA GBM dataset." (PMID 30636076, 2019).
lung carcinoma (1 paper, 2022). "CA10 and TMEM132, which were upregulated by passive smoking, are predicted risk factors for lung cancer and tinnitus, respectively." (PMID 35602164, 2022).
parathyroid carcinoma (1 paper, 2012). "The frame shift mutation in Ca5 had been reported previously in HPT-JT syndrome and missense mutation in Ca6, frame shift mutation in Ca10 had been reported in sporadic parathyroid carcinoma." (PMID 23029104, 2012).
pulmonary disease (1 paper, 2021). "Like CA10, DISC1 has ties to both pulmonary disease and viral infections." (PMID 34409086, 2021).
tumor (5 papers, 2019 to 2025). "To further explore the mechanisms involved in the potential capacity of Ca10 to promote Treg generation, we initially investigated the ability of this tumor-associated carbohydrate to regulate the phenotype and function of human DCs." (PMID 37990034, 2023). "To determine the potential molecular mechanisms by which Ca10 could promote Treg generation, we first studied the capacity of this tumor-associated carbohydrate to immunomodulate the phenotypic and functional features of human DCs." (PMID 37990034, 2023). "The administration of Ca10 to tumor-free mice also increases the proportion of splenic Tregs, which is fully impaired by the mAb A10 through the recognition of the saccharide portion of Ca10." (PMID 37990034, 2023). "The data show robust downregulation of CA10 expression in tumor tissues in these two large datasets." (PMID 30636076, 2019). "By using ET-bearing mice, as a paradigmatic tumor model with efficient tumor escape mechanisms capable of growing in hosts with very different genetic backgrounds, we observed positive correlations between the serum levels of Ca10, tumor size and splenic Treg frequency." (PMID 37990034, 2023). "Collectively, these results suggest that Ca10 shedding by ETs might promote the generation of Tregs, which in turn might favor tumor progression." (PMID 37990034, 2023). "Administration of isolated Ca10 also increases the proportion of splenic Tregs in tumor-free mice." (PMID 37990034, 2023). "Ca10 did not directly affect the migration or proliferation capacity of other adherent tumor cells." (PMID 37990034, 2023). "As observed for Tregs, Ca10 does not appear to have a direct effect on tumor cells." (PMID 37990034, 2023).
cancer (4 papers, 2017 to 2023). A tumor composed of atypical neoplastic, often pleomorphic cells that invade other tissues. "Remarkably, we provide evidence supporting the presence of a circulating human Ca10 counterpart (Ca10H) and show, for the first time, that serum levels of Ca10H are increased in patients suffering from different cancer types compared to healthy individuals." (PMID 37990034, 2023). "Intriguingly, several genes showing positive correlation in gene bodies have been previously linked to cancer, including MUC15, HEPACAM2, CA10, NRG1 and RAB25 (Mitra, Cheng & Mills, 2012)." (PMID 32832275, 2020). "Another interesting observation of the current study is that CA10 induced PERK axis is blocked by NAC pre-treatment, which shows that the anti-cancer effects of CA10 are ROS-dependent." (PMID 29254150, 2017).
neurological diseases (1 paper, 2023). "By consulting relevant literature, 6 genes related to neurodevelopmental and neurological diseases (GPC5, CA10, DSCAM, IL1RAPL2, CNTN2, and SPOCK3) were verified by ELISA method." (PMID 37539343, 2023). "Finally, six genes/proteins related to neurodevelopmental and neurological diseases (GPC5, CA10, DSCAM, IL1RAPL2, CNTN2, and SPOCK3) were verified by ELISA." (PMID 37539343, 2023).
CA10 also shares sentences with these, for which no sentence is quoted: bladder cancer (1 paper); diabetes (1); Holt-Oram syndrome (1); non-suppurative otitis media (1); preeclampsia (1); prostate carcinoma (1); Tinnitus (1); Wilms tumor (1).